MYCN (MYCN proto-oncogene, bHLH transcription factor)
Diseases named in the same sentence as MYCN in open-access papers (continued):
Sharing a sentence is not in itself a finding about the gene and the disease.
neuroblastoma (continued). "It has been reported that neuroblastoma patients bearing both MYCN amplification and ALK mutations are characterized by unfavorable aggressive neuroblastoma phenotype." (PMID 27049722, 2016). "While amplification of MYCN drives subsets of high-risk neuroblastoma and medulloblastoma, dysregulation of MYCN in medulloblastoma (in the absence of amplification) also contributes to pathogenesis." (PMID 26029667, 2015). "Currently, there are several mouse models with spontaneous neuroblastoma development such as those with amplified MYCN or mutated ALK." (PMID 26286454, 2015). "The MYC family member MYCN, which is associated with amplification in the childhood tumor neuroblastoma, is stabilized by Aurora-A in a kinase-independent fashion, but involves a direct protein–protein interaction." (PMID 26734566, 2015). "Apart from these, studies relating to [Ca2+]i on MYCN expression is questionable as neuroblastoma is often associated with MYCN over expression." (PMID 26010602, 2015). "The distribution of age and MYCN status was comparable in both cohorts, except exclusion of patients younger than 12 months with single-copy MYCN (MYCNsc) neuroblastoma in the high-risk COG cohort." (PMID 25267348, 2015). "Combining the drugs caused profound inhibition of proliferation of all neuroblastoma cell lines, independently from MYCN expression." (PMID 25477524, 2015). "Neuroblastoma prognosis frequently depends upon ploidy, loss of heterozygosity, pathology, and MYCN expression." (PMID 25973900, 2015). "The most extensively defined factor associated with neuroblastoma is the Myc oncoprotein family member MYCN, which is especially amplified in the most aggressive and often metastatic forms of neuroblastoma." (PMID 25266063, 2015). "The MYCN amplification was associated with an advanced stage of neuroblastoma and rapid progression." (PMID 26370236, 2015). "We were able to confirm a positive association between TRPM7 and MYCN mRNA expression in two out of five additional neuroblastoma patients datasets that are publically available." (PMID 25797249, 2015). "Genomic amplification of MYCN plays a dominant role in determining the biologic behavior of neuroblastoma and is strongly associated with advanced stage of the disease, rapid tumor progression, therapy resistance and overall poor prognosis." (PMID 26148557, 2015). "Amplification of MYCN occurs in 22% of cases of neuroblastoma and is associated with advanced stages of this disease and a poor prognosis." (PMID 25351211, 2015). "Amplification of the MYCN gene, which occurs in approximately 25% of human neuroblastomas overall and 40% of high-risk cases, remains the most important and reliable oncogenic marker." (PMID 26528759, 2015). "Since its discovery over 30 years ago in the childhood cancer neuroblastoma, MYCN has been implicated in a wide array of developmental and cancer-associated processes." (PMID 26673823, 2015). "For instance, neuroblastoma is a pediatric solid tumor associated with a high frequency of MYCN amplifications, and inhibition of BET proteins in neuroblastoma leads to cell arrest." (PMID 25849938, 2015). "Despite of the knowledge on MYCN amplification associated with neuroblastoma cell apoptosis, studies still confers the role of [Ca2+]i in inducing intrinsic apoptotic pathway." (PMID 26010602, 2015). "Depletion of PKMYT1 caused a drastic reduction of MYCN protein in most of the neuroblastoma cell lines analyzed." (PMID 25477524, 2015). "MYCN has been linked to numerous cancers and MYCN amplification status is the strongest single gene predictor of prognosis in neuroblastoma." (PMID 26673823, 2015).
neuroblastoma (continued). "When activated by amplification in a fraction (∼30%) of neuroblastomas, the protooncogene MYCN is a direct cause of the disease." (PMID 25477524, 2015). "Amplification of MYCN is the most well-known prognostic marker of neuroblastoma risk classification, but still is only observed in 25% of cases." (PMID 25266063, 2015). "The majority of metastatic, high risk neuroblastomas are characterized by the presence of MYCN amplification." (PMID 25477524, 2015). "Amplification of the MYCN gene is associated with an aggressive form of neuroblastoma that results in a particularly poor clinical outcome." (PMID 26734566, 2015). "Transgenic expression of MYCN in the neuroectoderm causes neuroblastomas in mice with features similar to those seen in the human disease." (PMID 25477524, 2015). "Amplification of the MYCN oncogene is now known to occur in approximately 20% of primary neuroblastomas and is consistently associated with poorer clinical outcome." (PMID 25860940, 2015). "Cocktails of small molecule inhibitors of CKS1B, AHCY, BLM, and PKMYT1 profoundly affected the growth of all neuroblastoma cell lines but selectively caused death of MYCN-amplified cells." (PMID 25477524, 2015). "Neuroblastoma is characterized by a wide range of clinical manifestations and associated with poor prognosis when there is amplification of MYCN oncogene or high expression of Myc oncoproteins." (PMID 26398947, 2015). "Neuroblastoma, especially high-risk stage 4 NB with MYCN amplification has limited treatment options and associated with poor prognosis." (PMID 25951238, 2015). "In this regard, MYCN-amplified neuroblastomas provide an attractive model for studying the molecular mechanisms that underlie the connection between N-Myc overexpression and glutamine addiction." (PMID 26528759, 2015). "The poor clinical outcome and aggressive tumor phenotype of high-risk neuroblastoma strongly correlates with amplification of the proto-oncogene MYCN and enhanced tumor angiogenesis." (PMID 24667968, 2014). "We have identified two parental imprinted miRNAs (miR-487b and miR-516a-5p) able to improve the current risk stratification of neuroblastoma based on age, stage, and MYCN amplification." (PMID 24931722, 2014). "The worst subtype of neuroblastoma is caused by MYCN oncogene amplification and N-Myc oncoprotein over-expression." (PMID 24586304, 2014). "The MYCN oncogene has a central role in the genesis and progression of neuroblastomas, and its amplification is associated with an unfavorable prognosis." (PMID 24391509, 2014). "Approximately half of unfavorable neuroblastoma cases have MYCN amplification, which is associated with high MYCN expression, older age of onset, advanced stage disease, rapid tumor progression, and the worst prognosis." (PMID 25017515, 2014). "Amplification of MYCN oncogene and consequent N-Myc oncoprotein over-expression occur in approximately 40% of high risk neuroblastoma, and is clinically associated with cancer metastasis, resistance to therapies and poor patient outcome." (PMID 24586304, 2014). "By contrast, in neuroblastomas, E2F2 was shown to positively regulate MYCN transcription and thought to be required for full activity of MYCN expression in aggressive neuroblastomas usually associated with poor prognosis." (PMID 25202354, 2014). "Differentiation as a target for therapy has been investigated and several groups are attempting to down regulate MYCN expression as a treatment in high-risk MYCN amplified neuroblastoma." (PMID 24679140, 2014). "MYCN amplification is detected in ∼20% of all neuroblastoma cases and is significantly associated with advanced stage disease, rapid tumor progression and shorter survival." (PMID 24173829, 2014).
neuroblastoma (continued). "Conversely, RNAi-mediated inhibition of MYCN expression in MYCN-amplified neuroblastoma cell lines causes a further increase in the proportion of cells undergoing ACD." (PMID 24965943, 2014). "Presence of amplified MYCN in neuroblastoma is associated with poor prognosis and rapid tumour progression." (PMID 24679140, 2014). "For example, the presence of the p.F1174L mutation was associated with a worse prognosis in MYCN-amplified neuroblastomas in one study, and resistance to crizotinib in another preclinical in vitro study." (PMID 25188507, 2014). "Age at diagnosis, stage, and MYCN amplification are the cornerstones of the risk-stratification score of neuroblastoma that enables defining patients at low- and high risk." (PMID 24931722, 2014). "Amplification of the MYCN proto-oncogene is found in 40–50% of high-risk neuroblastoma cases and is associated with increased vascular density, rapid tumor progression and poor survival." (PMID 24759734, 2014). "The majority of high-risk neuroblastoma exhibit amplification of the MYCN proto-oncogene and increased neoangiogenesis." (PMID 24759734, 2014). "Further studies targeting PAX3 gene expression in MYCN-amplified neuroblastoma cells will help to define the mechanisms associated with PAX3 gene function in this tumour." (PMID 24188742, 2014). "Here, we investigated the human neuroblastoma cell line SHEP-21N in which the MYCN oncogene (encoding N-Myc) can be reversibly expressed under control of an inducible repressor." (PMID 25277194, 2014). "Here we provide evidence for potent BET inhibitor activity in neuroblastoma, a pediatric solid tumor associated with a high frequency of MYCN amplifications." (PMID 24009722, 2013). "Recent studies suggested that overexpression of mutated ALK works cooperatively with MYCN overexpression to promote the severity of induced neuroblastoma." (PMID 23667670, 2013). "Several recurring genomic alterations have been found often associated with poor outcome in neuroblastoma, which include MYCN amplification, 1p and 11q deletion, and ALK activating mutations." (PMID 24147068, 2013). "Here we determined that expression of miR-497, another potential tumor suppressor in neuroblastoma, was significantly lower in high-risk MYCN amplified tumors and that lower miR-497 expression was associated with worse EFS and OS in our patient cohort." (PMID 23531080, 2013). "Currently, the strongest predictive risk factors used for neuroblastoma risk stratification are age, stage, tumor histology, and MYCN gene amplification status." (PMID 24348903, 2013). "Treatment of human neuroblastoma cell lines with retinoic acid causes a significant decrease in MYCN RNA expression and arrest of cell proliferation." (PMID 23292364, 2013). "Low PPARδ and ALOX5 expression was associated with MYCN amplification in a cohort of 251 primary neuroblastoma tumours." (PMID 23874790, 2013). "Among the apoptosis-associated genes identified in the microarray was BCL2, an anti-apoptotic gene that is highly expressed in a number of tumor types and associated with MYCN-amplification and unfavorable histology in neuroblastoma." (PMID 24009722, 2013). "Here we show that a novel BET inhibitor, I-BET726, exhibits potent anti-proliferative activity in models of neuroblastoma, a solid tumor associated with a high frequency of MYCN gene amplifications." (PMID 24009722, 2013). "Amplification of the MYCN gene has emerged as one of the most reliable indicators of aggressive and treatment-resistant neuroblastoma, yet 30% to 40% of high-risk tumors lack this feature." (PMID 24348903, 2013).
neuroblastoma (continued). "In contrast, Mdm2 deficiency suppressed MYCN driven neuroblastoma tumorigenesis, as evident by an extended tumor latency and survival and reduced tumor incidence and growth in TH-MYCNMdm2 +/− transgenic mice compared with TH-MYCNMdm2 + / + mice." (PMID 23226679, 2012). "Based on age, staging, MYCN amplification status, histology, and DNA ploidy, neuroblastoma is classified into low, intermediate and high risk groups." (PMID 22436457, 2012). "About half of the high-risk neuroblastoma patients are characterized by the MYCN amplification (MNA) status, which represents the most relevant independent negative prognostic factor in neuroblastoma." (PMID 23091802, 2012). "Campothecin and topotecan caused selective down-regulation of B-Myb and MycN expression in neuroblastoma cells." (PMID 22619121, 2012). "The TH-MYCN mice develop neuroblastoma-like tumors, due to a deficient process of neural crest cell deletion during early life, demonstrating that high MYCN expression can initiate tumorigenesis." (PMID 23284678, 2012). "A typical feature of high-risk disease is MYCN amplification which occurs in ~25% of neuroblastoma, associating with rapid tumor progression and a poor prognosis." (PMID 23226679, 2012). "MYCN amplification occurs in about 20–25% of human neuroblastomas and characterizes the majority of the high-risk cases, which display less than 50% prolonged survival rate despite intense multimodal treatment." (PMID 23152863, 2012). "Amplification of MYCN is the most common genetic aberration associated with poor outcome in neuroblastoma, occurs in roughly 30% of primary tumours and is strongly correlated with advanced disease and treatment failure." (PMID 22619121, 2012). "Amplification of the gene encoding the MYCN transcription factor is the most potent genetic predictor of poor patient outcome and delineates a distinct genetic subtype of high-risk neuroblastoma." (PMID 22164278, 2011). "Our results demonstrated a significant role of alternative splicing in high stage neuroblastoma, and suggested a MYCN-associated splicing regulation pathway in stage 4+ tumors." (PMID 21501490, 2011). "The wide spectrum of biological and clinical behaviours of neuroblastoma has resulted in basic risk stratification parameters (age, stage and MYCN amplification) that discriminate high-risk from low-risk patients." (PMID 21970883, 2011). "Combination of age at diagnosis, stage and MYCN amplification stratifies neuroblastoma into low-risk and high-risk." (PMID 21970883, 2011). "Neuroblastomas are particularly problematic in that some genetic subtypes, such as those exhibiting amplification of the MYCN oncogene or deletion of chromosome 11q, are associated with very poor patient survival in spite of intensive multimodal chemotherapy." (PMID 21266077, 2011). "Amplification of the MYCN oncogene is a well established poor prognostic factor found in up to 40% of high risk neuroblastomas." (PMID 21194500, 2011). "It needs to be determined if the loss of CASP8 and/or maspin expression can be a prognostic marker for Breast Cancer and if it is associated with amplification of MYCN (v-myc myelocytomatosis viral related oncogene), as frequently observed in neuroblastomas." (PMID 20132554, 2010). "MYCN amplification is a very important risk factor in neuroblastoma and correlates with unfavorable prognosis." (PMID 20624283, 2010). "The importance of MYCN in risk assessment is shown by the fact that MYCN gene is amplified, and often over-expressed, in about 22% of all neuroblastoma patients and it is an independent predictor for poor prognosis." (PMID 20624283, 2010).
neuroblastoma (continued). "As a first step in the construction of the MAQ neuroblastoma assay, primers were designed in the critical regions of loss (1p, 3p and 11q) and gain (2p -more specifically the MYCN locus- and 17q) for NB and their respective opposite chromosome arm." (PMID 20459859, 2010). "MYCN amplification is associated with metastatic disease and poor survival of neuroblastoma patients." (PMID 21304178, 2010). "Transgenic expression of MYCN in the neuroectoderm causes neuroblastoma in mice, demonstrating its causative role in this disease." (PMID 21304178, 2010). "The amplification and overexpression of MYCN primarily found in 25% of neuroblastomas are associated with advanced tumour stage, tumour progression and poor outcome." (PMID 20017904, 2009). "Amplification of the MYCN oncogene is already used clinically as a prognostic marker to stratify treatment in neuroblastoma and cMyc has been linked to a more aggressive phenotype in medulloblastoma." (PMID 19208232, 2009). "Amplification of the MYCN transcription factor was one of the first genetic abnormalities to be associated with poor clinical outcome in neuroblastoma." (PMID 19924232, 2009). "We conclude that there is widespread dysregulation of miRNA expression in neuroblastoma tumors caused by both over-expression of the MYCN transcription factor and by large-scale chromosomal imbalances." (PMID 19924232, 2009). "High resolution aCGH analysis was carried out on all 145 primary neuroblastoma tumours in order to identify DNA copy number alterations and to classify the tumors into major genetic subtypes (MYCN amplified, chromosome 11q loss etc)." (PMID 19924232, 2009). "In Neuroblastoma, we identified the three known subgroups, and the MYCN amplification known to be associated with one of the types." (PMID 19352461, 2009). "Amplification of MYCN is a genetic abnormality found in approximately one third of all human neuroblastomas and closely associated with advanced stage and poor outcome." (PMID 19730731, 2009). "While the clinical diversity of neuroblastoma correlates with several genetic features, such as ploidy or allelic loss, the amplification of the MYCN gene is the best genetic marker of poor prognosis." (PMID 18493594, 2008). "High MYCN/c-MYC target gene expression is a hallmark of malignant neuroblastoma progression, which is predominantly driven by c-MYC in stage 4-non-amplified tumors." (PMID 18851746, 2008). "Differences in MYCN/c-MYC target gene expression are associated with distinct neuroblastoma subtypes and clinical outcome." (PMID 18851746, 2008). "We identified a key oncogenic pathway underlying neuroblastoma progression: specifically, MYCN, expressed at elevated level, transactivates the miRNA 17-5p-92 cluster, which inhibits p21 and BIM translation by interaction with their mRNA 3′ UTRs." (PMID 18493594, 2008). "In this study, we have investigated the molecular mechanisms underlying MYCN-induced neuroblastoma progression." (PMID 18493594, 2008). "We observed a significantly weaker expression of ACCN1 in neuroblastomas with MYCN amplification (p<0.01) or with 1p36 loss of heterozygosity (p<0.01) compared to tumors without these alterations." (PMID 18493581, 2008). "In MYCN single-copy neuroblastomas, elevated MYCN mRNA and protein levels are paradoxically associated with a more favorable clinical phenotype, including disseminated tumors that subsequently regress spontaneously (stage 4s-non-amplified)." (PMID 18851746, 2008). "Our work describes a novel oncogenic pathway underlying neuroblastoma development, whereby MYCN transactivates the miRNA 17-5p-92 cluster, which in turn downmodulates the tumor suppressors p21 and BIM." (PMID 18493594, 2008). "An example is the deletion of chromosome band 1p36, which is strongly correlated with MYCN gene amplification, a very poor prognostic marker in neuroblastoma, and which by itself is also commonly associated with an advanced disease stage and a poor outcome." (PMID 17327916, 2007).